ROR1 (ROR family WNT receptor 1)
Diseases named in the same sentence as ROR1 in open-access papers (continued):
Sharing a sentence is not in itself a finding about the gene and the disease.
breast cancer (continued). "Glucocorticoids reportedly promote metastasis in preclinical models of metastatic breast cancer through GR-mediated activation of ROR1 specifically in metastatic breast cancer cells." (PMID 33115754, 2020). "Another study showed that the interaction of the surface protein ROR1 expressed in breast cancer cells interacts with cortactin and plays an important role in breast cancer cell migration and metastasis." (PMID 32210163, 2020). "Altogether, these data suggest that ROR1 modulation regulates chemo drug efficacy in breast cancer cells in vitro." (PMID 32020017, 2020). "Using breast cancer PDX models, paclitaxel treatment stimulated ROR1 expression that was associated with CSC enrichment, spheroid formation, tumor invasiveness, and tumorigenicity." (PMID 31394796, 2019). "As a matter of fact, ROR1 was identified as one of the few kinases specifically upregulated in a well-defined model of breast cancer stem cell phenotype." (PMID 30832318, 2019). "Immunoblot analyses of anti-ROR1 or anti-cortactin immune precipitates confirmed that cortactin complexed with ROR1 in breast-cancer PDX cells." (PMID 31667337, 2019). "ROR1 signaling promotes breast cancer migration and survival via downstream activation of the P13K/AKT pathway resulting GSK3ß inhibition." (PMID 31150511, 2019). "In the present study, we found that Wnt5a induces ROR1 to associate with cortactin, which undergoes tyrosine phosphorylation in breast-cancer PDX cells or MCF7 cells transfected to express ROR1." (PMID 31667337, 2019). "Focused studies in breast cancer pointed to the role of ROR1 in enhanced tumor cell growth, epithelial-to-mesenchymal transition (EMT), and metastasis." (PMID 30832318, 2019). "It should be noted that in these studies, cirmtuzumab was injected on the same day on which mice were challenged with cancer cells injected intravenously to study the effect of blocking ROR1 signaling on circulating breast-cancer cells." (PMID 31667337, 2019). "Mass spectrometry (MS) analyses of anti-ROR1 mAb immune precipitates (i.p.)from lysates of ROR1-expressing breast-cancer PDX revealed cortactin in addition to ROR1." (PMID 31667337, 2019). "In conclusion, the present study demonstrates a previously unrecognized ROR1/cortactin/ARHGEF1-dependent pathway leading to activation of RhoA in response to Wnt5a in breast-cancer cells." (PMID 31667337, 2019). "Further evidence for ROR1 involvement in CSCs has emerged from studies of ovarian and breast cancers." (PMID 31382410, 2019). "It has also been shown to disrupt the activity of pathways downstream to ROR1 such as P13K/AKT in breast cancer." (PMID 31150511, 2019). "In any case, this study provides added rationale for the clinical evaluation of this humanized anti-ROR1 mAb in the treatment of patients with breast cancer or other ROR1-expressing cancers." (PMID 31667337, 2019). "Further analysis revealed that ROR1 expression was associated with increased YAP/TAZ activity, and ROR1high breast cancer cells expressed genes associated with M CSC phenotypes, providing an additional link between YAP/TAZ and M CSCs." (PMID 31394796, 2019). "Collectively, these studies demonstrate that the interaction of ROR1 with cortactin plays an important role in breast-cancer-cell migration and metastasis." (PMID 31667337, 2019). "In breast cancer, Wnt5a binding to ROR1 increases BMI-1 levels and this process was dependent on AKT phosphorylation." (PMID 31382410, 2019). "Similar findings have been described in the T-DM1-induced drug resistance of breast cancer cells, which resulted in elevated ROR1 levels." (PMID 31382410, 2019). "A transcriptome analysis of breast cancer metastasis indicated a direct correlation between ROR1 levels and GR (glucocorticoid receptor) signaling activation." (PMID 31382410, 2019). "GR activation increased metastatic breast cancer development in a ROR1-dependent manner, while decreasing the efficacy of paclitaxel." (PMID 31382410, 2019).
breast cancer (continued). "For instance, Wnt5a and Wnt5b were found to be overexpressed in basal-like MDA-MB-231 cells compared to less aggressive LumA MCF-7 cells and their expression levels were also elevated together with Ror1/Ror2 in breast cancer brain metastases." (PMID 28695110, 2017). "Recently, high ROR1 expression was also observed in acute lymphocytic leukemia, chronic lymphocytic leukemia, ovarian cancer, gastric cancer, breast cancer and lung cancer." (PMID 28427197, 2017). "Ror1 was significantly more expressed in various tumours such as acute lymphocytic leukemia, renal carcinoma, breast cancer, lung cancer, adenocarcinoma and melanoma." (PMID 28432357, 2017). "Silencing ROR1 expression by siRNA reduces the expression of EMT-associated proteins, such as SNAIL-1/2, ZEB1, CXCR4, and vimentin in breast cancer cell line MDA-MB-231." (PMID 27830754, 2016). "To further investigate the impact of ROR1/2 overexpression in breast cancer cells, we transfected both the luminal A breast cancer cell line MCF-7 and the ERBB2/HER-2+ cell line SK-BR-3 with a ROR2 construct." (PMID 26862065, 2016). "Segueing into breast cancer, ROR1 has been shown to be expressed in human neoplastic breast cancer cells, while remaining absent within stromal cells." (PMID 24752542, 2014). "ROR1 is highly expressed in early embryonic stages and in diverse cancers such as human breast cancer and B-cell chronic lymphocytic leukemia." (PMID 24920305, 2014). "Silencing expression of ROR1 in human breast cancer cell lines found to express this protein impaired their growth in vitro and also in immune-deficient mice." (PMID 22403610, 2012). "Because of this, we interrogated published DNA microarray datasets on primary human breast cancers and cancer cell lines for expression of ROR1 and hormone receptors." (PMID 22403610, 2012). "We noted that many of the breast cancer cell lines included in a dataset published by Neve and colleagues had levels of ROR1 comparable to that of MDA-MB-231 or MDA-MB-468." (PMID 22403610, 2012). "This allowed us to examine tissue microarrays for expression of ROR1 by neoplastic breast cancer specimens of different patients (N = 113) or by normal adult breast tissues (N = 15)." (PMID 22403610, 2012). "Our results reveal that human breast cancers express ROR1, which can contribute to tumor-cell growth and survival via activation of PI3K, AKT, and CREB." (PMID 22403610, 2012). "Patients who had primary breast cancers that expressed higher levels of ROR1 had a significantly shorter median survival than did patients with primary breast cancers that had low-to-negligible expression of ROR1." (PMID 22403610, 2012). "In either dataset, we found that primary breast cancers that expressed high-levels of ROR1 were more likely to lack expression of estrogen or progesterone receptors or HER2/Neu, consistent with the observation in breast cancer cell lines." (PMID 22403610, 2012). "Notably, a few malignant tumors, such as breast cancer, have high expression levels of ROR1 as well." (PMID 39755633, 2025). "Additionally, ROR1 expression is prevalent in solid tumors such as ovarian cancer, breast cancer, particularly triple-negative breast cancer (TNBC), and lung cancer." (PMID 41479906, 2025). "Additionally, it was observed that treatment of Hs578T breast cancer with the humanized anti-ROR1 monoclonal antibody cirmtuzumab decreased sphere formation and invasion compared to control in the presence of WNT5A." (PMID 40869147, 2025). "Further evaluation of ROR1 targeting in breast cancer patients with zilovertamab is warranted." (PMID 38408999, 2024). "Further evaluation of ROR1 expression and ROR1 targeting in breast cancer is warranted." (PMID 38408999, 2024). "Furthermore, TCGA breast cancer data show similar expression of EMT markers between ROR1-high and -low groups." (PMID 38296962, 2024).
breast cancer (continued). "Using breast cancer cell lines and patient samples, this study identified small and large EVs as a novel mode of transportation for spreading ROR1 and ROR2 within the local tumor microenvironment as well as the hematological system where they can be used as cancer biomarkers." (PMID 37430307, 2023). "In the present study, we used breast cancer cell lines as well as patient samples to investigate whether the two Wnt co-receptors ROR1 and ROR2 can be spread via EVs." (PMID 37430307, 2023). "Stress hormone GC is the natural agonist of GR in humans, and its increase during breast cancer progression leads to the activation of the receptor and increased expression of kinase ROR1 at distant metastatic sites, increases colonization, and reduces survival in mice models." (PMID 37114049, 2023). "Many cancers, including breast cancer, have an overexpression of the ROR1." (PMID 37779899, 2023). "Additionally, experimental downregulation of ROR1 has been shown to inhibit cell proliferation and induce apoptosis in breast cancer cells." (PMID 37779899, 2023). "We performed hierarchical clustering of ROR1 with 24 EMT-related genes including the Hippo signaling pathway genes from the MSigDB database along with WNT5a, BMI1, BCL2, and GLI1 prompted by associations noted in prior studies on breast cancer or CLL." (PMID 37029329, 2023). "This study highlights the potential prognostic value in assessing the levels of ROR1 and/or ROR2 in untreated high-risk early-stage breast cancer and justifies further studies to evaluate the biology and possible value of targeting ROR1 and ROR2 with investigational treatments." (PMID 37029329, 2023). "However, several studies have shown that ROR1 is highly expressed in neoplastic cells in many different types of cancers, such as leukemia, breast cancer, and ovarian cancer." (PMID 36557069, 2022). "In another study, YAP1 was found to regulate ROR1 expression, and Wnt5A/ROR1–YAP1/TAZ feedback loop was associated with cancer stem cell phenotype, tumor progression, metastasis, and, ultimately, drug resistance of breast cancer." (PMID 35053353, 2022). "Furthermore, a phase I clinical trial of ROR1-CAR-T cell therapy was initiated to study the side effects and optimal dose in ROR1-positive cancers including stage IV breast cancers and metastatic TNBC (NCT02706392)." (PMID 35414783, 2022). "miR30a can inhibit expression of Ror1 to suppress the progression of breast cancer, however, its expression level is reduced in breast cancer cells, resulting in up-regulation of Ror1 and promotion of the progression of breast cancer." (PMID 35493090, 2022). "The type of the tumor may also contribute to this discrepancy because in the present study we employed syngeneic ROR1-expressing mouse colon and breast cancer cell lines, whereas in our previous study HER2-expressing rat breast tumor cell line was used." (PMID 36497309, 2022). "Interestingly, breast cancer brain metastases have likewise been shown to highly express ROR1, hinting at its role in metastatic spread." (PMID 33445713, 2021). "Consequently, cancer cells with reduced expression of ROR1 or ROR2 were characterized by a significantly impaired potential in forming metastases in mouse models of melanoma or breast cancer." (PMID 33445713, 2021). "In the past years, considerable energy has been put into evaluating the safety of cirmtuzumab in clinical trials (phase I and II) in hematological B cell malignancies, where it had been identified as a tumor marker, then extending its use to ROR1-expressing solid tumors, such as breast cancer." (PMID 33445713, 2021). "Concordantly, in breast cancer cells ROR2 overexpression augmented ROR1 levels." (PMID 33445713, 2021). "Moreover, in a Src kinase -omics identification analysis of MCF10A breast cancer epithelial cells, it was found that ROR1 and SGK1 are located in different regulatory branches, thus suggesting an independent pathway as revealed by our study." (PMID 34272474, 2021).
breast cancer (continued). "The aberrantly expressed ROR1 has been extensively suggested to play a pivotal role in the process of different varieties of cancers or malignant cells, including gastric cancer, breast cancer, ovarian carcinoma, and pancreatic cancer." (PMID 34421987, 2021). "Activation of Yap pathway target genes induces bone metastasis in breast cancer through signaling pathways involving ROR1, HER3 and lncRNA MAYA61." (PMID 33972619, 2021). "ROR1 is another emerging target in breast cancer and other cancer types." (PMID 33670942, 2021). "We also demonstrate that ROR1 inhibition potentiates chemo drug response in breast cancer cells." (PMID 32020017, 2020). "Next, we sought to investigate whether glucocorticoids could modulate ROR1 expression in OC as recently demonstrated in breast cancer preclinical models." (PMID 32989221, 2020). "Wnt5a also induced ROR1-dependent tyrosine phosphorylation of cortactin (Y421), which recruited ARHGEF1 to activate RhoA and promote breast-cancer-cell migration; such effects could be inhibited by cirmtuzumab, a humanized mAb specific for ROR1." (PMID 31667337, 2019). "Interestingly, in tumors such as breast cancer, enhanced ROR1 expression promotes tumorigenesis through the upregulation of YAP/TAZ transcription and/or polycomb complex protein BMI-1 expression." (PMID 31382410, 2019). "ROR1 is a conserved oncoembryonic surface protein expressed in breast cancer." (PMID 31667337, 2019). "Furthermore, breast cancer patients expressing Ror1 and Ror2 have been reported to show a poor survival." (PMID 28695110, 2017). "In particular Ror1/2 receptors and several other members of the non-canonical Wnt signaling pathway were associated with aggressive breast cancer behavior." (PMID 28695110, 2017). "To investigate activation and outcome of the Ror2-dependent non-canonical Wnt signaling pathway, we overexpressed the Ror2 receptor in MCF-7 and MDA-MB231 breast cancer cells, stimulated the cells with its ligand Wnt5a, and we knocked-down Ror1 in MDA-MB231 cells." (PMID 28695110, 2017). "Because literatures showed that high level of ROR1 expression in breast cancer tissues, while their adjacent non-tumor tissues has little expression, so we first took advantage of tissue samples of breast cancer patients to validate the specificity of ROR1 antibody." (PMID 27830754, 2016). "We also found that 7 of 12 (55%) patients with lobular breast adenocarcinoma had breast cancer tissue that had high-level expression of ROR1, whereas only 21 of 71 (29%) patients with ductal breast adenocarcinoma had cancer tissue that stained intensely with 4A5." (PMID 22403610, 2012). "We silenced ROR1 expression in breast cancer cell lines to evaluate its function on tumors." (PMID 22403610, 2012). "Two individual gene expression data were used to evaluate whether breast cancers that expressed ROR1 had clinical significance distinct from that of ROR1-negative tumors." (PMID 22403610, 2012). "This study demonstrates that ROR1 is expressed in human breast cancers and has biological and clinical significance, indicating that it may be a potential target for breast cancer therapy." (PMID 22403610, 2012). "Here we present data demonstrating that high proportions of human breast cancers expressed ROR1." (PMID 22403610, 2012). "Here, we used a high-affinity mAb specific for ROR1 (named 4A5) to examine human breast cancers." (PMID 22403610, 2012). "Studies have shown that ROR1 is expressed on CSCs in chronic lymphocytic leukemia, mantle cell lymphoma, glioblastoma, neuroblastoma, osteosarcoma, pancreatic, gastric, fallopian, endometrial, ovarian, and breast cancer, and its inhibition can affect the maintenance of these cells." (PMID 40869147, 2025). "Therefore, we examined the expression of genes that may be upregulated in breast cancer cells through activation of ROR1 or ROR2 signaling." (PMID 37029329, 2023). "However, ROR1-targeted CAR-T cells showed limited efficacy in breast cancer." (PMID 35935930, 2022).
breast cancer (continued). "Meanwhile, studies on breast cancer primary cells have likewise identified a population of cells carrying the cancer stem cell markers ALDH1+/CD44+/CD24low that displayed particularly high ROR1 expression and showed enhanced growth of tumor spheres in vitro as well as tumorigenicity in vivo." (PMID 33445713, 2021). "IHC analyses have demonstrated a wide-spread expression of ROR1 across many tumor entities with significantly higher expression levels in cancerous than in adjacent normal tissue, including a particularly strong expression in melanoma, colon, pancreatic, lung, and breast cancer." (PMID 33445713, 2021). "More recently, GR activation has been observed in breast cancer metastases and was associated with a GR activation signature which included genes such as MELK, CDK1, and particularly the ROR1 kinase, which may mediate resistance to chemotherapeutic agents and increase colonization." (PMID 31675993, 2019). "Nonetheless, we found that cirmtuzumab could inhibit the capacity of Wnt5a to induce tyrosine phosphorylation of cortactin in serum-starved ROR1+breast-cancer PDX, even at Wnt5a concentrations of 100 ng/ml, indicating that the Wnt5a-induced phosphorylation of cortactin was dependent on ROR1." (PMID 31667337, 2019). "While this study primarily focused on ROR1-expressing NSCLC, the therapeutic efficacy of this combination approach in other ROR1-positive malignancies, such as ovarian or breast cancer, remains to be explored." (PMID 39849645, 2025). "Receptor Tyrosine Kinase-like Orphan Receptor 1 (ROR-1) is involved in embryonal development, and it is highly expressed in breast cancer and related to its growth." (PMID 40332761, 2025). "CAR T cell-based therapy for breast cancer also targets RTK, including AXL, hepatocyte growth factor receptor (HGFR), and receptor tyrosine kinase-like orphan receptor 1 (ROR1)." (PMID 39755633, 2025). "Among breast cancer patients with higher residual disease burden after neoadjuvant therapy for HR+/HER2− breast cancer, patients with high-level expression of ROR1 had significantly worse event-free survival than those with low-level expression of ROR1." (PMID 38408999, 2024). "Recent studies have shown that the Receptor tyrosine kinase-like orphan receptor 1 (ROR1) is highly expressed in TNBC, making it a potential candidate for targeted therapy in this type of breast cancer." (PMID 38167105, 2024). "While both ROR1 and ROR2 are only detectable at low levels in healthy tissue, they are found overexpressed in breast cancer primaries as well as metastases." (PMID 37430307, 2023). "Previous studies have shown that ROR1-CAR T cells inhibit tumor development in lung and breast cancers." (PMID 37770853, 2023). "Recent studies have revealed that this applies also to ROR1 and ROR2 as both have been observed to be heterogeneously expressed in pancreatic and mammary tumors in vivo." (PMID 37430307, 2023). "In this study we detected the Wnt co-receptors ROR1 and ROR2 on EVs from breast cancer cell lines and patients and thus identified a novel mode for spreading Wnt/ROR signaling across tissues." (PMID 37430307, 2023). "ROR1-CAR-specific autologous T-lymphocytes have been developed, and a phase I trial is ongoing for leukemia/lymphoma, non-small cell lung carcinoma, and breast cancer (NCT02706392)." (PMID 37241228, 2023). "In order to confirm that EVs can indeed transport ROR1 and ROR2, we isolated the main EV subpopulations, LOs, lEVs, and sEVs, from the conditioned medium of the three breast cancer cell lines by using differential ultracentrifugation." (PMID 37430307, 2023). "We examined the relationship between gene expression of ROR1 and/or ROR2 and outcomes in breast cancer patients enrolled in the “Investigation of Serial Studies to Predict Your Therapeutic Response with Imaging And Molecular Analysis 2” (I-SPY2 TRIAL) study." (PMID 37029329, 2023).